S100A3 (S100 calcium binding protein A3)
Diseases named in the same sentence as S100A3 in open-access papers:
S100A3 is named in the same sentence as 34 diseases in open-access papers, as found by Europe PMC text mining. Sharing a sentence is not in itself a finding about the gene and the disease. The quoted sentences say what the papers report.
ovarian carcinoma (6 papers, 2018 to 2024). A malignant neoplasm originating from the surface ovarian epithelium. "Among these genes, S100A3 belongs to the S100 family and is considered to be associated with a good prognosis of ovarian cancer, which is similar to our results." (PMID 34349789, 2021). "While, in breast cancer, the loss of S100A3 expression was associated with malignant development, which was in accordance with its favorable prognosis in ovarian cancer in our study." (PMID 30558666, 2018). "Thus, the knockdown of S100A11 expression suppresses ovarian cancer cell growth and invasion, and S100A3 expression is associated with chemoresistance of cancer cells." (PMID 38339228, 2024). "Elevated expression of S100A3 was found primarily in ovarian cancer cells resistant to cisplatin and paclitaxel, both standard chemotherapeutic drugs, as well as topotecan, a chemotherapeutic agent commonly used in second-line treatment." (PMID 32722137, 2020). "Nevertheless, among others, S100A3, S100A10, and S100B were identified to be related to drug resistance in ovarian cancer." (PMID 32722137, 2020). "Whereas, some other S100 family members, including S100A3, S100A5, S100A7, S100A7A, S100A8, S100A16 and S100G are less reported in ovarian carcinoma." (PMID 30558666, 2018). "FAM198B may act to favor tumor progression by interacting with numerous genes, such as the p-ERK/MMP-1 signaling pathway in lung adenocarcinoma, and S100A3, PCDH9, and SEMA3A genes in ovarian cancer." (PMID 35587159, 2022). "Up to now, the prognostic role of S100A3 in ovarian cancer has not been reported." (PMID 30558666, 2018).
gastric cancer (5 papers, 2008 to 2021). A primary or metastatic malignant neoplasm involving the stomach. "The present work confirmed for the first time that S100A3 was upregulated in gastric cancer and associated with the poor differentiation and higher TNM stage of gastric cancer cells." (PMID 18793447, 2008). "It was also reported that S100A3 was relatively highly expressed in poorly differentiated and advanced gastric cancer." (PMID 30558666, 2018). "We provided evidence that at least five S100 genes were upregulated in gastric cancer and further experimentally verified the upregulation of S100A3 by quantitative RT-PCR." (PMID 18793447, 2008). "Correlation of S100A3 mRNA expression with clinicalpathological parameters in patients with gastric carcinoma." (PMID 18793447, 2008). "However, in gastric cancer, the high expression of S100A3 is closely in relation to the poor survival of patients." (PMID 34349789, 2021). "All these data demonstrated that S100A3 was overexpressed in gastric cancer specimens and might be related to the differentiation and development of gastric cancer." (PMID 18793447, 2008). "Next we evaluated the expression of S100A3 in gastric cancer tissues by quantitative RT-PCR." (PMID 18793447, 2008). "However, the role of S100A3 in differentiation and progression of gastric cancer needed to be further investigated." (PMID 18793447, 2008). "The expression of S100A3 in eighty patients of gastric cancer was further examined." (PMID 18793447, 2008). "The results indicated that overexpression of S100 gene family members were characteristics of gastric cancers and S100A3 might play important roles in differentiation and progression of gastric cancer." (PMID 18793447, 2008). "Our work suggested that in silico analysis is a valid strategy for discovering differentially expressed genes in gastric cancer, and S100A3 was a novel overexpressed gene in gastric cancer cells and might play an important role during the differentiation and progression of gastric cancer." (PMID 18793447, 2008). "The results showed that the mean expression levels of S100A3 in gastric cancer tissues were 2.5 times as high as in adjacent non-tumorous tissues." (PMID 18793447, 2008). "S100A3 was demonstrated to be overexpressed in gastric cancer by dataset GSE2669 and GSE2701, which did not existed in dataset GSE3438." (PMID 18793447, 2008). "The relatively mean expression level of S100A3 in gastric cancer was 2.52 ± 1.45 when compared to adjacent non-tumorous tissues (p = 0.01)." (PMID 18793447, 2008). "S100A3 expression was correlated with tumor differentiation and TNM (Tumor-Node-Metastasis) stage of gastric cancer, which was relatively highly expressed in poorly differentiated and advanced gastric cancer tissues (P < 0.05)." (PMID 18793447, 2008). "Furthermore, S100A3 expression is correlated with tumor differentiation and TNM in gastric cancer." (PMID 29027969, 2017). "To investigate whether S100A3 was overexpressed in gastric cancer, we examined the mRNA expression of S100A3 in gastric cancer tissues and corresponding adjacent non-tumorous tissues of 80 patients by quantitative RT-PCR." (PMID 18793447, 2008).
lung carcinoma (5 papers, 2018 to 2025). "S100A3 knockdown reduced the amount of RARα in breast and lung cancer cells, and thus induced resistance to ATRA differentiation, suggesting that S100A3 is an important regulatory factor affecting breast and lung cancer cell differentiation." (PMID 34148033, 2021). "S100A3 knockdown decreases the amounts of RARα in breast- and lung cancer cells, inducing resistance to ATRA-dependent anti-proliferative/differentiating effects." (PMID 30532072, 2019). "The interaction of S100A3 with RARα is direct and in lung cancer, APL and acute-myeloid-leukemia (AML) cells." (PMID 30532072, 2019). "In addition to its role in idiopathic pulmonary fibrosis (IPF), S100A3 is also a potential drug target in lung cancers." (PMID 34239729, 2021). "We considered breast cancer SK-BR-3 and MCF-7 cells, lung cancer A-549 cells as well as APL-derived and PML-RARα+NB4 blasts which synthesize measurable levels of S100A3 and RARα." (PMID 30532072, 2019). "The interaction of S100A3 with RARα is observed in breast cancer and lung cancer, acute-myeloid-leukemia (AML) as well as acute promyelocytic leukemia (APL) cells, in which S100A3 binds also to PML-RARα." (PMID 30532072, 2019). "The control exerted by S100A3 on RARα modulates the anti-tumor activity of ATRA in breast cancer SK-BR-3 and lung cancer A549 cells." (PMID 30532072, 2019). "However, the roles of S100A1, S100A3, S100A7A, S100A12, S10016, and S100G proteins in lung cancer are rarely reported." (PMID 29607329, 2018).
colorectal cancer (4 papers, 2013 to 2018). A primary or metastatic malignant neoplasm that affects the colon or rectum. "In colorectal cancer, the high level of S100A3 were related to the tumor occurrence and progression." (PMID 30558666, 2018). "Immunohistochemical staining shows cell membrane and cytoplasmic expression of S100A3 in human colorectal cancer and surrounding normal tissue; however, expression is much higher in tumor tissue." (PMID 29027969, 2017). "The expression level of S100A3 was increased in human colorectal cancer cells compared that in normal control cells." (PMID 28611294, 2017).
prostate carcinoma (4 papers, 2017 to 2021). A carcinoma that arises from epithelial cells of the prostate gland. "Some researchers reported that inhibiting the expression of S100A3 significantly reduced the invasion ability of prostate cancer and inhibited tumor growth." (PMID 34148033, 2021). "In human castration-resistant prostate cancers, the expression level of S100A3 was increased and inhibiting its expression resulted in the suppression of tumour growth." (PMID 28611294, 2017). "In castration-resistant prostate cancer cells, S100A3 inhibition reduced invasion and tumor growth." (PMID 30558666, 2018). "A more prominent role of S100A3 was observed in gastric and prostate cancers." (PMID 29027969, 2017).
breast carcinoma (3 papers, 2018 to 2019). "Induction of ATRA-resistance is consistent with the primary role exerted by RARα in mediating the anti-tumor action of the retinoid in breast cancer and the decrease in the levels of RARα afforded by S100A3 knockdown." (PMID 30532072, 2019). "Given the key-role played by RARα in mediating ATRA anti-proliferative action in breast cancer cells, we also investigated the consequences of S100A3 silencing on ATRA-dependent growth inhibition of SK-BR-3 cells." (PMID 30532072, 2019). "In ATRA-sensitive breast cancer cells, S100A3 binds to RARα in basal conditions and binding is reduced by the retinoid." (PMID 30532072, 2019).
lung fibrosis (3 papers, 2023 to 2025). "S100A3 and S100A13 mutations are particularly relevant in the context of familial early-onset pulmonary fibrosis (PF), with our research showing that these mutations disrupt key cellular processes that contribute to fibrosis." (PMID 41164170, 2025). "Recently, two variants in the calcium-binding protein genes S100A3 (NM_002960) and S100A13 (NM_001024210) were identified, segregating with the disease in seven siblings from two unrelated families with pulmonary fibrosis." (PMID 40497957, 2025). "The importance of their normal function is evident from the observation that simultaneous mutations in S100A3 and S100A13 predispose individuals to early-onset pulmonary fibrosis, underscoring their critical role in lung health." (PMID 41164170, 2025). "Patients with digenic S100A3 and S100A13 mutations exhibited an atypical and progressive interstitial pulmonary fibrosis, with impaired intracellular calcium homeostasis and mitochondrial dysfunction." (PMID 38099297, 2023). "This iPSC disease model is the first to replicate the role of S100A3 and S100A13 in lung fibrosis." (PMID 40497957, 2025).
glioma (2 papers, 2021 to 2025). A benign or malignant brain and spinal cord tumor that arises from glial cells (astrocytes, oligodendrocytes, ependymal cells). "S100A3, S100A4, S100A8, and S100A9 expression was up-regulated during the progression of glioma grade." (PMID 34148033, 2021). "There are relatively few studies on S100A2 and S100A3 genes in glioma immunity, and there is no sufficient evidence to show their specific role in glioma immunity at present." (PMID 34148033, 2021).
African trypanosomiasis (1 paper, 2014). "Regarding the 16 up-regulated genes, S100A3, AXL, IL12A, XPC and FAS identified GO terms such as positive regulation of natural killer cell activation, response to UV-B, African trypanosomiasis, allograft rejection and Type I diabetes mellitus." (PMID 24756038, 2014).
astrocytic tumor (1 paper, 2020). A glial tumor of the brain or spinal cord showing astrocytic differentiation. "For example, modifications in the level of S100A3 protein expression level could help identify the pilocytic astrocytomas from WHO grade II-IV astrocytic tumors." (PMID 31968004, 2020).
bladder cancers (1 paper, 2013). "The differential expression of S100A3 has been implicated in the bladder cancers." (PMID 24396594, 2013).
brain tumors (1 paper, 2021). "However, the role of S100A2 and S100A3 in brain tumors has been less well studied." (PMID 34148033, 2021).
celiac disease (1 paper, 2013). An autoimmune genetic disorder with an unknown pattern of inheritance that primarily affects the digestive tract. "There has been a surge in studies that have produced results indicating that the dysregulated expression and function of S100A3 contributes to pathological conditions, such as cancer metastasis, celiac disease and diseases associated with defective assembly." (PMID 24255681, 2013).
head and neck cancer (1 paper, 2017). A primary or metastatic malignant neoplasm affecting the head and neck. "In head and neck cancers, expression of the S100A3 gene is upregulated in comparison to normal mucosa." (PMID 29027969, 2017).
hepatocellular carcinoma (1 paper, 2021). A malignant tumor that arises from hepatocytes. "In hepatocellular carcinoma (HCC), S100A3 expression is associated with tumorigenesis and tumor aggressiveness." (PMID 34148033, 2021).
inflammatory skin disease (1 paper, 2024). Inflammatory skin disorders covers a broad category that includes many conditions ranging in severity, from mild itching to grave medical health complications These disorders are common in people of all ages and races. "After analysing the RNA‐seq data, we discovered that Livin expression influenced the release of antimicrobial peptides such as S100A3, S100A7, and BD1 from KCs, which have been demonstrated to play important roles in many inflammatory skin diseases and could be increased following UVB exposure." (PMID 38332512, 2024).
insomnia (1 paper, 2026). A sleep disorder characterized by difficulty in falling asleep and/or remaining asleep. "Among them, S100A3 showed consistent discriminatory performance across the training cohort, the independent sleep deprivation cohort, and the insomnia cohort, whereas VEGFB exhibited notable diagnostic potential, particularly in insomnia." (PMID 42216239, 2026).
lymph node metastasis (1 paper, 2008). "The results showed that S100A3 mRNA expression did not correlated with gender, age, tumor size, depth of wall invasion, microscopic subtypes or lymph node metastasis with a statistic p > 0.05 in each parameter." (PMID 18793447, 2008).
metastatic tumors (1 paper, 2017). "Higher expression in poorly differentiated and in metastatic tumors suggests that S100A3 plays a role in drug resistance, since poorly differentiated tumors as well as metastatic ones are usually more resistant to chemotherapy than are well differentiated primary tumors." (PMID 29027969, 2017).
osteosarcoma (1 paper, 2022). A usually aggressive malignant bone-forming mesenchymal neoplasm, predominantly affecting adolescents and young adults. "The expression of BNIP3, SLC38A5, CKMT2, CXCL11, SLC5A3, S100A3, and PGM1 genes was verified in osteosarcoma cells (Saos-2 and 143B) and normal osteoblasts (hFOB1.19)." (PMID 36578780, 2022).
uncombable hair syndrome (1 paper, 2019). Uncombable hair syndrome (UHS), or pili trianguli et canaliculi, is a rare scalp hair shaft dysplasia. "Other downregulated genes, namely PADI3 and TCHH are associated with uncombable hair syndrome in humans and S100A3 has been connected with an age-dependent damage of the hair cuticle." (PMID 30794648, 2019).
tumor (15 papers, 2008 to 2025). "We found that the transcriptional levels of S100A3/A5/A6/A10/A11/A14/A16/B/P/Z were correlated with tumor stage." (PMID 34804125, 2021). "The present study demonstrated that the level of S100A3 was increased in the process of tumor occurrence and progression, and that S100A3 expression in human CRC was inhibited by cantharidinate." (PMID 24255681, 2013). "For example, the levels of expression of the S100A3 proteins differed markedly in the astrocytic tumour tissue in relation to the tumour types and grades." (PMID 18793447, 2008). "The S100A3 expression levels in well- and moderate-differentiated tumor tissues were both significantly lower than that in poorly differentiated ones (p < 0.05)." (PMID 18793447, 2008). "Activated and overexpressed S100A3 is associated with tumorigenesis, tumor occurrence, and progression of CRC, and S100A3 may be a potential target for CRC treatment." (PMID 33294444, 2020). "To evaluate whether modulation of S100A3 expression has any consequence on ATRA anti-tumor activity, we took a silencing approach." (PMID 30532072, 2019). "Furthermore, S100A3 mRNA levels correlated with tumor differentiation, with low expression in well- and moderate-differentiated tumors and high expression in poorly differentiated ones." (PMID 29027969, 2017). "In in vivo studies, tumor growth was significantly reduced in mice injected with PC3 and DU145 cells transfected with S100A3 shRNA, in comparison to the control." (PMID 29027969, 2017). "The expression of S100A3 increased notably in the CRC tissues, with the expression predominantly in the tumor and tumor interstitial regions." (PMID 24255681, 2013). "In contrast, several S100 genes had similar expression levels across multiple tumour types, including S100A14, S100A13 and S100A3." (PMID 18781180, 2008). "To evaluate whether S100A3/RARα interaction is a general phenomenon, we performed co-immunoprecipitation studies in ATRA-sensitive tumor cell lines of different origin." (PMID 30532072, 2019). "However, we found that the expression of S100A3 mRNA was correlated with tumor differentiation and Tumor-Node-Metastasis stage." (PMID 18793447, 2008).
cancer (8 papers, 2013 to 2025). A tumor composed of atypical neoplastic, often pleomorphic cells that invade other tissues. "In the present study, the protein expression of S100A3 was observed in a cohort of 20 patients with cancer, which indicated that S100A3 activation was involved in tumorigenesis." (PMID 24255681, 2013). "The expression of S100A3 mRNA in the cantharidinate group decreased to 0.88-fold that of the untreated cancer cell controls (P<0.05)." (PMID 24255681, 2013). "The samples were collected as part of a trial comparing the expression of S100A3 in carcinoma and control tissues." (PMID 24255681, 2013). "S100A3 plays an important role in tumorigenesis and progression of a variety of human cancers." (PMID 33294444, 2020). "Increased expression of S100A3 in different cancers suggests a role for it in cancer development." (PMID 29027969, 2017). "Also, the increased expression of S100A3 was observed in the progression of different cancers." (PMID 39940891, 2025). "For example, the over-expression of S100A2, S100A3, S100A6, S100A8/A9, S100A11 and S100A14 have been documented in several cancer types." (PMID 30018736, 2018). "For example, over-expression of S100A2, S100A3, S100A6, S100A8/A9, and S100A11 is related to several types of cancer, whereas other types of cancer are characterized by the under-expression of these same proteins." (PMID 25988147, 2014). "In contrast, increased expression of the S100A3 and HERC5 genes was described in different cancers." (PMID 29027969, 2017). "In our study, gene expression analyses show that S100A2, S100A11, and S100P expression levels in CRC tissues are significantly higher than those in noncancerous tissues, and S100A3 and S100A9 mRNAs are highly expressed in cancer tissues compared with normal tissue controls." (PMID 33294444, 2020).
S100A3 also shares sentences with these, for which no sentence is quoted: acute myeloid leukemia (1 paper); acute promyelocytic leukemia (1); astrocytomas (1); diabetes (1); idiopathic pulmonary fibrosis (1); infection (1); lung adenocarcinoma (1); medulloblastoma (1); myeloid leukemia (1); pilocytic astrocytoma (1); type 1 diabetes mellitus (1).